CD14 (CD14 molecule)
Diseases named in the same sentence as CD14 in open-access papers (continued):
Sharing a sentence is not in itself a finding about the gene and the disease.
melanoma (continued). "We report that the presence of CD14+ cDC2s in melanoma patients interferes with the effectiveness of autologous DC vaccines." (PMID 38242119, 2024). "The enrichment of CD1c+CD14+ cells with low immunostimulatory capability in melanoma and NSCLC prompted us to study their development." (PMID 38242119, 2024). "Melanoma patient-derived CD1c+ DC vaccine preparations containing a larger fraction of CD14+ cells significantly hampered T cell activation." (PMID 38242119, 2024). "Culture with HD serum showed that a fraction of cDC2s upregulates CD14, which slightly increases with melanoma patient serum." (PMID 38242119, 2024). "In the here used human M-MDSC model, we observed that upon exposure to melanoma CM, moMDSCs further acquired a suppressive phenotype, characterized by the upregulation of CD14, CCR5, MerTK, and the downregulation of HLA-DR and CD86." (PMID 38343540, 2024). "In NSCLC and melanoma patients, the majority of CD1c+ cells, on average 59% and 68%, respectively, expresses CD14." (PMID 38242119, 2024). "identify tumor-induced CD1c+CD14+ DC3s, increased in melanoma and NSCLC patients, originating from DC2s upon exposure to tumor-derived IL-6 and M-CSF." (PMID 38242119, 2024). "In the peripheral blood of stage III and IV melanoma patients, CD1c+CD14+ frequencies were increased compared with healthy individuals." (PMID 38242119, 2024). "In 3D melanoma co–cultures CD11c+/CD14+ cells increased in 20 kPa gels while CD11c+/CD317+ cell populations remained unchanged along with CD11c+/STAT5p+ populations." (PMID 39211033, 2024). "These miRNAs were elevated in circulating CD14+ monocytes, plasma, and tumor samples of melanoma patients and correlated with the myeloid cell infiltration in melanomas." (PMID 39126091, 2024). "We found that almost the entire CD14+ subset and the majority of CD11c+ cells in patients with melanoma express Dectin-1." (PMID 38668817, 2024). "In melanoma patients undergoing CD1c+ DC vaccinations, increased CD1c+CD14+ DC frequencies correlate with reduced survival." (PMID 38242119, 2024). "Another study into CD14+ DCs showed that melanoma cells drove cDC2s to CD14+ DCs in a human organotypic skin culture." (PMID 38242119, 2024). "Strengthening these findings, in vitro melanoma-induced CD14+ DCs displayed impaired T cell activation compared with CD14− DCs." (PMID 38242119, 2024). "The IL-10 secreted in high levels by melanoma promote the trans-differentiation of moDCs into tolerogenic CD14+ BDCA3+ macrophage-like cells similar to the one enriched in melanoma metastases." (PMID 37190135, 2023). "These CD14+HLA−DRno/low cells isolated from melanoma patients significantly reduced the IFN‐γ secretion of T cell in the cocultures of GPNMB+ MDSCs and autologous activated T cells." (PMID 38140790, 2023). "Incubating CD14+ monocytes for 24 h with EVs isolated from melanoma cell cultures, authors observed the differentiation of the cells towards a new phenotype that they called EV-MDSCs." (PMID 36831417, 2023). "Similar results were obtained incubating CD14+ monocytes for 24 h with EVs isolated from the plasma of patients with advanced melanoma." (PMID 36831417, 2023). "The transition of CD14+ monocytes into MDSCs (CD14 + HLA-DRneg cells) was induced in vitro by secreted extracellular vesicles from melanoma cells." (PMID 36982460, 2023). "Consistent with our results, single cell analysis revealed that high levels of CD14+CD16- HLADRhigh monocytes before ICI correlated with significantly increased PFS in melanoma patients and NSCLC patients." (PMID 37638022, 2023). "A recent study demonstrated that once injected into a human organotypic melanoma culture, cDC2 can follow two different fates: become tolerogenic or acquire the CD14+ monocytic marker." (PMID 36230990, 2022). "In contrast, CD14+ CD1c+ DC have been shown in blood of healthy controls and melanoma patients, albeit showing immune-inhibitory functions." (PMID 36685500, 2022).
melanoma (continued). "Some immunity-related proteins were detected in melanoma, like CD14 as a particular protein in stage II melanoma and upregulated Endoglin/CD105." (PMID 36338621, 2022). "Of note, two-dimensional culture of human melanoma cells with DCs revealed that prostaglandin E2 and IL-6 released from the melanoma cells converted cDC2s into CD14+ cDCs, which are characterized by an immunosuppressive phenotype." (PMID 35454882, 2022). "In patients with stage IV melanoma, the high frequency of CD14+ CD16− HLA-DRhi monocytes in peripheral blood samples before anti-PD-1 immunotherapy was a strong predictor of PFS and OS in response to PD-1 immunotherapy." (PMID 36013407, 2022). "We also examined a separate cohort of melanoma patients and found a similar elevation of CD14+CD33+ monocytes in patients responsive to PD-1 blockade." (PMID 35493454, 2022). "Of these, PON3, CD14 and RAP1B were evaluated for their association with survival in the primary melanoma sample data set of the TCGA." (PMID 34439311, 2021). "In particular, CD14+ myeloid cells isolated from melanoma cells have been demonstrated to develop a suppressive activity on T cells when disposed with extracellular vesicles (EVs), thus referred to as EV-MDSCs." (PMID 34336860, 2021). "CD1c+CD14+ cells are detected in a variety of cancers, such as ovarian, breast cancer, and melanoma." (PMID 34359719, 2021). "In the UC cohort, the frequency of neutrophils, classical CD14+ monocytes, plasmacytoid dendritic cells (pDCs) and myeloid-derived suppressor cells (MDSCs) was higher compared to the melanoma cohort." (PMID 34071888, 2021). "Similar to our findings, CD14+CD1c+ found in melanoma patients showed a higher degree of uptake compared to CD1c+ DCs." (PMID 34359719, 2021). "Overall, this ex vivo analysis of tumour biopsies highlights the phenotypic similarity between CD14+ DCs reprogrammed within OMCs and those isolated from melanoma lesions." (PMID 32488012, 2020). "In fact, treatment of CD14+ monocytes with melanoma-derived or colorectal carcinoma-derived EV impaired their ability to differentiate into DC." (PMID 32878277, 2020). "In particular, it has been demonstrated that CD14+ cells exposed to extracellular vesicles (EVs) (containing proteins, lipids, and genetic material) isolated from melanoma cells, show a suppressive activity on T cells thus referred as EV-MDSCs." (PMID 32849585, 2020). "In this study, four MDSC subsets were analyzed in the PBMCs of advanced melanoma patients, at baseline and 12 weeks after Ipilimumab: CD14+IL-4Rα+ M-MDSCs, CD14+HLA-DRlow/− M-MDSCs, Lin−HLA-DR−CD33+CD11b+ eMDSCs, and CD15+IL4-Rα+ PMN-MDSCs." (PMID 32793228, 2020). "In blood of melanoma patients with metastatic disease, the frequency of the CD14+ subset of CD1c+ cells in blood was found to be increased more than three-fold." (PMID 33101275, 2020). "Subsequently, we set out to compare CD14+ DCs induced in the OMC with myeloid cells isolated from melanoma lesions of stage IV metastatic melanoma patients." (PMID 32488012, 2020). "In one study, melanoma-derived EV have been demonstrated to skew monocyte differentiation towards suppressive CD14+HLA-DR-/low cells, which also lose the expression of costimulatory molecules CD80 and CD86." (PMID 32878277, 2020). "In patients with liver cancer or advanced melanoma, CD14+HLA-DR−/low MDSCs suppress autologous NK-cell cytotoxicity and IFN-γ production." (PMID 32793192, 2020). "Together, these findings were taken to design an optimized cellular vaccine, in which the CD14+ subset is removed from the CD1c+ DC product for vaccination of patients with melanoma and other malignancies." (PMID 33101275, 2020). "Tumor-infiltrating CD14+CD1c+ DCs have been reported in multiple instances, including ovarian cancer ascites, breast cancer, and melanoma." (PMID 32610077, 2020).
melanoma (continued). "Using flow cytometry analysis, we identified CD14+ DCs (green) and cDC2s (orange) in melanoma lesions, similarly to what we previously observed within OMCs." (PMID 32488012, 2020). "Functionally, the melanoma-induced CD14+ DCs described here, express genes (such as SSP1, PTGS2, IL-6) previously associated with immunosuppressive myeloid cells and, like monocytes and macrophages, have poor T-cell stimulatory ability." (PMID 32488012, 2020). "Intriguingly, CD14+ DCs developed within the organotypic melanoma cultures shared important phenotypic similarities with CD14+ DCs infiltrating human melanoma lesions." (PMID 32488012, 2020). "The impact of CD14+HLA-DRlo/neg monocytes on CTLA-4 inhibition with ipilimumab has most clearly been demonstrated in melanoma patients with advanced disease." (PMID 31191529, 2019). "Their expression of CD14 suggests a joint origin with MDSCs, that are also significantly elevated in melanoma patients." (PMID 30235890, 2018). "The monocytes associated with melanoma are restrained in their expression of CD80 and CD86 co-stimulatory molecules but retain CD14 and HLA class II expression, thus finally promoting the expansion of CD11b+/Gr-1+ MDSCs." (PMID 29755693, 2018). "In vitro experiments showed that monocytes can differentiate towards cells phenotypically resembling BDCA1+CD14+ cells when cultured in the presence of serum of melanoma patients." (PMID 30235890, 2018). "In 2016, we identified a population of BDCA1+CD14+-immunosuppressive cells that was present both in blood and tumor of melanoma patients." (PMID 30235890, 2018). "Naïve and memory CD4+ T-cell stimulation.Th17 polarization.DC-10, skin CD141+CD14+ DCs and CD1c+CD14+ DCs in melanoma patients promote tolerance." (PMID 29250057, 2017). "Another DC population characterized by CD1c+CD14+CD16− expression was found in the blood of melanoma patients and exhibited immunosuppressive functions by suppressing T-cell proliferation in an antigen-specific manner." (PMID 29250057, 2017). "The number of CD14+/HLA-DRlow/- cells was shown to be elevated in melanoma patients and this increase correlated with melanoma disease activity." (PMID 26788324, 2016). "The highest frequencies of CD14+HLA-DR- MDSC were observed in melanoma patients compared to healthy donors (p = 0.2)." (PMID 26176858, 2015). "After CD14+HLA-DR- MDSC were initially reported to be increased in melanoma patients, this observation was subsequently expanded to other cancer types such as prostate and renal cell cancer (RCC)." (PMID 26176858, 2015). "Flow cytometric analysis of VEGFR1 in the MDSC fraction of CD11B+ cells (defined as CD11B+ CD14− HLA− CD33+) also revealed elevated protein levels in stage IV melanoma patients compared with controls (unpaired t-test, P<0.001)." (PMID 25924227, 2015). "Next, we investigated the frequency of the immune regulatory cell subsets present in the peripheral blood of melanoma patients prior to survivin-specific vaccination; for this analysis, we focussed on Th17 cells, Tregs and CD14+HLA-DR- MDSC." (PMID 26176858, 2015). "Here, we confirmed that CD14+HLA-DRlow cells, isolated from peripheral blood mononuclear cells obtained from melanoma patients, have the ability to suppress the proliferation of autologous CD8+ T cells in a dose-dependent manner." (PMID 25149535, 2014). "For instance, the fraction of CD3+ T cells, and most notably CD8+ T cells, was consistently lower in PBMC from melanoma patients, whereas the opposite was found for CD14+ monocytes." (PMID 25101086, 2014). "A population of CD14+HLA-DRlow cells with suppressive activity on T cells has been described for several tumor types, including melanoma." (PMID 25149535, 2014). "A recent study found that the percentage of CD14+CD16+ monocytes was significantly increased in PBMC from melanoma patients exposed to IFNα ex vivo." (PMID 22363505, 2012).
melanoma (continued). "We prepared immature DCs (IDCs) from CD14+ cells isolated from leukapheresis products and extracted total RNA from freshly resected melanoma tissue." (PMID 16911798, 2006). "Melanoma TAMs (CD14+/CD51−) differentiated into osteoclasts (CD14−/CD51+) in the presence of receptor activator for nuclear factor κB ligand (RANKL) and macrophage-colony stimulating factor." (PMID 16641914, 2006). "Melanoma cells diverted the differentiation of CD34+ cells towards a dominant CD14+ population only if the progenitors were in an early growth phase." (PMID 11747338, 2001). "CD14+CD16−CD33+HLA-DRhi monocytes were found to predict response to anti-PD-1 therapy in melanoma, supporting the findings that this subpopulation of monocytes has a role in anti-tumor activity and to those potential mechanisms of therapeutic efficacy, and their analysis as mechanisms of resistance." (PMID 41282765, 2025). "Additionally, they showed that CD14+ cDC2s cells from melanoma patients had decreased T cell proliferation and activating capacity compared to canonical cDC2s, and blood CD14+ cDC2s (de facto DC3s) numbers relate to lower survival rates." (PMID 40584260, 2025). "Finally, based on the observed systemic effect of tumors on CD1c+CD14+ cell frequencies in patients, we cultured CD14− cDC2s with melanoma patient or HD serum." (PMID 38242119, 2024). "In addition, a moderate positive correlation is observed between ENG and MCAM (Melanoma Cell Adhesion Molecule), as well as between CD14 and CD44." (PMID 39594703, 2024). "Furthermore, additional research has indicated that in cases of melanoma, CD14(+) cells exert a suppressive influence on autologous T cells through a STAT-3, prostaglandin E2 (PGE2), and O2•− dependent mechanism." (PMID 37469162, 2024). "In this work, we focus on tumor-induced CD14+ DCs arising in melanoma and NSCLC patients." (PMID 38242119, 2024). "A previous finding has suggested that circulating CD14 (+)CD16(−)HLA-DR(hi) monocytes could predict benefits of immunotherapy in melanoma." (PMID 38660677, 2024). "In addition, CD14+ DCs are found in the tumors of melanoma patients and express high levels of PD-L1, allowing the inhibition of T-cell proliferation." (PMID 37190135, 2023). "However, there is an expansion of a population of BDCA1+CD14+ cells (possibly corresponding to DC3s) expressing PD-L1 in melanoma patients, which can be found in DC vaccines, and responsible for suppressing CD4 T-cell responses." (PMID 37190135, 2023). "Moreover, a DC signature (CD14+CD2+LY75+) associated with stromal macrophages linked with antigen capture and presentation was found associated with long-term survival of melanoma patients." (PMID 37190135, 2023). "In addition, higher levels of CD14+ and BDCA1+ CD14+ cells (moDC) have been found in melanoma skin metastatic lesions in comparison with healthy skin." (PMID 35406451, 2022). "The CD14+ cDC2 population, previously identified in tumor settings as cDC2/moDCs, is also detected in melanoma lesions, characterized by immunosuppressive function and higher expression of additional macrophage-like markers (CD163, CD206, MerTK) and PD-L1 in comparison to CD14− cDC2s." (PMID 36230990, 2022). "In melanoma patients, the frequency of the CD1c+CD14+ cells increased, and for the DC vaccination strategy used in these patients, CD1c+CD14+ cells were omitted from the optimized protocol and might be even a potential target to improve immunotherapy." (PMID 34359719, 2021). "A highly significant elevation of ID1 was observed in CD33+CD11b+CD14+HLA-DRlow monocytic MDSC in the blood of melanoma patients compared to their HLA-DRhigh counterparts, while expression of ID1 correlated positively with established MDSC markers S100A8/9 and iNOS." (PMID 31953577, 2020).
melanoma (continued). "In regionally advanced melanoma patients treated with neoadjuvant Ipilimumab, circulating CD14+HLA-DRlow/− M-MDSC levels were lower at baseline but tended to increase, although not reaching statistical significance, in the relapse-free group, while frequencies in the relapsed group remained stable." (PMID 32793228, 2020). "Furthermore, the CD1c+ CD14+ inf-DC-like populations that accumulate in melanoma nodules are hypostimulatory for allogenic T cells and have high cell surface expression of PD-L1." (PMID 30979057, 2019). "Moreover, an increased TGF-β production by CD14+HLA-DRlow/− M-MDSCs from patients with melanoma was shown to be PGE2 and COX2 dependent." (PMID 30936876, 2019). "A population of CD1c+ CD14+ DC that may be related to inf-DC have been detected in skin lesions of melanoma patients." (PMID 30979057, 2019). "Future studies should reveal whether BDCA1+CD14+ cells are also present in these types of leukemia and if these cells have the same immunosuppressive capacity, as was shown in melanoma patients." (PMID 30235890, 2018). "HLA DR+/lo CD14+ MDSC have been detected specifically in melanoma patients." (PMID 29973204, 2018). "In melanoma and colon cancer, TEXs could curb peripheral CD14+ monocytes differentiating into DC cells, while inducing them into myeloid-derived suppressor cells (MDSCs)." (PMID 28642882, 2017). "Comparing to those in normal control, higher CD11b+CD14+HLA-DR− TGF-β secreting cells could be found in the peripheral blood of stages II-III melanoma patients, but minor boost in stage IV patients." (PMID 28642882, 2017). "Interestingly, we identified a myeloid-derived suppressor cell CD14+PD-L1+FKBP51s+ in peripheral blood of melanoma patients, expressing high TGF-β levels and apparently associated with resistance to ipilimumab." (PMID 28978117, 2017). "In melanoma patients, it was demonstrated that the proliferation and cytokine production (IFNγ) of autologous non-specific stimulated T cells were suppressed by 40% at the physiological ratios of CD14+HLA-DR-/low MDSC to T cells (1:4)." (PMID 27598210, 2016). "Moreover, TGF-β, and not Arg1 or iNOS, was shown to be involved in the suppressive capacity of CD14+HLA-DRlow/− cells obtained from melanoma patients." (PMID 27598210, 2016). "However, in our cohort of melanoma patients the increased frequencies of CD14+HLA-DR- MDSCs were correlated with metastatic stage, whereas Th17 cells and Treg frequencies were not." (PMID 26176858, 2015). "Human immature myeloid cells from advanced stage cancer patients inhibit allogeneic or tetanus toxoid specific T cell responses, while CD14+ myeloid suppressor cells in melanoma patients inhibit polyclonally activated IFN-γ secretion and proliferation of human T cells." (PMID 23717444, 2013). "Tumour-associated macrophages isolated from secondary melanomas expressed the monocyte/macrophage marker CD14 and were negative for the osteoclast markers TRAP and VNR and incapable of carrying out lacunar resorption." (PMID 16641914, 2006). "Interestingly, by performing spatially resolved transcriptomic analysis of CD14+ cells from different localization in melanoma tumor sections, the group of K. Palucka identified a DC signature (CD14+CD2+LY75+) in the stroma linked with antigen capture and presentation." (PMID 37190135, 2023). "This MDSC model was produced by exposing blood CD14+ monocytes to tumor extracellular vesicles, a process leading to cells highly overlapping for phenotype, immunosuppressive function, and transcriptional profiles with MDSCs isolated from blood of melanoma patients." (PMID 34185403, 2021). "added melanoma-derived microvesicles to CD14+ monocytes and observed that the cells retained CD14 status, had HLA-DR (−/low) expression, could not upregulate co-stimulatory molecules, and exhibited an inhibitory function via transforming growth factor (TGF)-β against T cells." (PMID 33738337, 2021).